INS (insulin)
Diseases named in the same sentence as INS in open-access papers (continued):
Sharing a sentence is not in itself a finding about the gene and the disease.
type 2 diabetes (continued). "DINAS‐AR was a national prospective observational study to assess the unmet needs in patients with type 2 diabetes treated with basal insulin with or without oral antihyperglycaemic drugs and/or GLP‐1 receptor agonist." (PMID 33532606, 2021). "Type 2 diabetes or non-insulin-dependent diabetes results from the combination of resistance to insulin action or/and inadequate insulin secretion." (PMID 34540481, 2021). "With respect to type 2 diabetes, people experience more stigma when on insulin than when on a noninsulin anti-diabetic drug." (PMID 33496671, 2021). "In type 2 diabetes, insulin will not be produced in an adequate amount, which will not be sufficient for body needs, which leads to type 2 diabetes." (PMID 34462631, 2021). "First, the main study population comprised individuals with NGM, prediabetes, or type 2 diabetes, who are generally not the target population for closed-loop insulin delivery systems." (PMID 34166426, 2021). "On the other hand, obesity itself comprises several pathological features such as impaired insulin signaling, beta cell dysfunction, low-grade chronic inflammation and oxidative stress, which all result in insulin resistance (IR), and ultimately, in type 2 diabetes mellitus onset (T2DM)." (PMID 34445049, 2021). "Type 2 diabetes mellitus (T2DM) is a complex chronic disease characterised by metabolic disorder and hyperglycaemia due to insulin resistance, hepatic glucose overproduction and/or insufficient insulin secretion." (PMID 31656107, 2020). "Type 2 diabetes (i.e. non-insulin-dependent, T2D) is a chronic, multifactorial, metabolic disorder typical of late adulthood characterised by less effective hormone insulin efficiency at lowering blood sugar." (PMID 33308172, 2020). "In adults with type 1 or type 2 diabetes, 25% reported rationing insulin in the previous year to manage costs, 3.2% reported rationing insulin on a daily basis, and 40% reported not discussing underuse with their physician." (PMID 33274701, 2020). "Type 2 diabetes (T2D) arises when pancreatic β-cell insulin secretion fails to meet insulin demands, which increase due to insulin resistance secondary to obesity." (PMID 33137873, 2020). "The relationship between NAFLD and type 2 diabetes mellitus (T2DM) has been well proven, which could be described by the insulin challenge and compensatory hyperinsulinemia advancing to faulty lipid metabolism and hepatic triglyceride (TG) increase in NAFLD or to b-cell malfunction in T2DM." (PMID 33053793, 2020). "Linagliptin was added to metformin and/or Insulin, in subjects with type 2 diabetes and Stage I–III chronic kidney disease but without any established adverse cardiovascular event (such as history of myocardial infarction or cerebral stroke)." (PMID 32493344, 2020). "Comorbidities included a urinary tract infection, metabolic syndrome with obesity, type-2 diabetes without necessity for insulin or oral antidiabetics, and non-alcoholic fatty liver disease." (PMID 32019572, 2020). "In a randomized, double-blind, placebo-controlled study in patients with type 2 diabetes 2, 5, 10 mg NGM282 (sc injection once daily for 12 weeks) did not correct hyperglycemia while a significant improvement in insulin sensitivity was observed at the high dose at the end of the study." (PMID 33414764, 2020). "In addition, given the fact that SIRT6 regulates insulin signaling and the expression of the glucose transporters GLUT1 and GLUT4, we previously tested 1 in a mouse model of type 2 diabetes." (PMID 32736564, 2020). "The consumption of an artificially sweetened soft drink containing acesulfame K and aspartame did not alter glucose, insulin, and insulin sensitivity during 2 weeks in individuals without Type 2 diabetes." (PMID 33291649, 2020).
type 2 diabetes (continued). "In an experimental model of spontaneous type 2 diabetes (KK-Ay mice), treatment for 4 weeks with 16:1n7 (300 mg/kg per day) increased insulin sensitivity and decreased the glycemic curve after glucose tolerance test (GTT) and plasma insulin concentration." (PMID 33117273, 2020). "Epidemiological studies have revealed a strong link between obesity and type 2 diabetes with the development of NASH, suggesting that an insulin-resistant milieu may be an important initial driving force for the development of NASH." (PMID 33343375, 2020). "During the first 10 years of follow-up, the development of type 2 diabetes was rare in women without insulin treatment for GDM, but thereafter the disease progression curve was almost linear and parallel to that of women on insulin for GDM." (PMID 32725280, 2020). "In our previous study, supplementary Cr3 (about 5 mg Cr/kg b.m.)normalized the liver Zn content in type 2 diabetic rats, but there were no changes in insulin-resistant model of rats." (PMID 30826908, 2020). "Similar to type 2 diabetes, PA might also prevent LADA through reducing overweight and insulin resistance or improving insulin secretion." (PMID 32835373, 2020). "It has been observed that add-on therapy with insulin markedly decreased the functional and cognitive decline as compared to regular therapy without insulin in individuals with type 2 diabetes and mild-to-moderate AD." (PMID 32380758, 2020). "Insulin maintains glucose homeostasis by reducing post-prandial blood glucose concentrations, and in a background of obesity and type 2 diabetes, insulin fails to control blood glucose levels." (PMID 32575897, 2020). "With progression to type 2 diabetes insulin fails to suppress hepatic glucose production yet promotes lipid synthesis." (PMID 32366255, 2020). "In patients with type 2 diabetes, we found generally a significant genotype effect; such that individuals with B1B1 genotype showed a significant decrease in apoB, apoB: apoA-1, insulin, and HOMA-IR and also an increase in QUICKI compared with B2B2 homozygotes." (PMID 33123324, 2020). "Although it has been shown that long-term supplementation of NMN improves glucose intolerance and lipid profiles in a mouse model of age-induced type-2 diabetes, our data suggests that high-dose NMN within a week is sufficient to reduce blood lipids and improve insulin sensitivity." (PMID 33384603, 2020). "These post-prandial effects of PA breaks on measures of glucose, insulin and TAG could be relevant to the prevention of type 2 diabetes and atherosclerosis." (PMID 31552570, 2020). "Our results indicated that in patients with type 2 diabetes who were being treated with basal insulin, the HbA1c reduction by post-meal walking or one prandial insulin injection were not different at 6 weeks." (PMID 32236116, 2020). "Different etiology characterizes Type 1 (T1D) and Type 2 diabetes (T2D) both featuring lack of insulin." (PMID 33302345, 2020). "In type 2 diabetes, insulin release does not compensate for the body’s needs due to β-cell dysfunction and/or insulin resistance." (PMID 32053947, 2020). "A family history of type 2 diabetes does not attenuate exercise-induced improvements in insulin sensitivity in young healthy Mexican-Americans." (PMID 32231642, 2020). "Many patients with type 2 diabetes in Asia often show non-obesity and impairment of insulin secretion." (PMID 33244056, 2020). "In addition to the well-known markers of glucose metabolism: HOMA-IR, glucose and insulin, resistin, leptin and PAI-1 are also related to type 2 diabetes (T2D)." (PMID 32872136, 2020). "This study indicated that high-dose RCEG (≥0.08 g/kg/d) can improve HbA1c, FPG and total cholesterol and is safe for patients with type 2 diabetes with or without OHA/insulin therapy." (PMID 33568997, 2020).
type 2 diabetes (continued). "After the failure of metformin monotherapy, over 90% of patients with type 2 diabetes reached their individual HbA1c goal with additional application of NPH insulin without any event of severe hypoglycaemia over several years." (PMID 32316649, 2020). "Insulin is no longer considered as the first choice for type 2 diabetes, and an expanding range of new therapeutic possibilities is emerging." (PMID 33167495, 2020). "It’s been reported that the incidence of DR is 39% in patients with type II diabetes who do not need insulin treatment, and the incidence of DR in patients with type II diabetes who require insulin is 70%." (PMID 32770964, 2020). "In a recent study, we have investigated the modulation of immunological parameters in insulin-treated type 2 diabetic patients, without pregnancy." (PMID 32626786, 2020). "Our results indicate that the TRIF-dependent TLR signaling contributes to maintaining insulin/AKT signaling and M2 macrophages in epididymal adipose tissue under a normal chow diet and provide new evidence that TLR4-targeted therapies for type 2 diabetes require caution." (PMID 33376487, 2020). "A parallel study of BFKB8488A in type 2 diabetes patients recapitulated improvements in HDL-cholesterol, triglycerides, and adiponectin, but did not demonstrate improvements in HbA1c, fasting glucose, or fasting insulin." (PMID 33381084, 2020). "Her known comorbidities included a metabolic syndrome with obesity (her height was 1.62 m, weight 93 kg, and body mass index 35.4 kg/m2), arterial hypertension, type-2 diabetes without oral antidiabetics or necessity for insulin, and dyslipidemia." (PMID 32019572, 2020). "The aim of this randomized comparative study was to assess renal and metabolic effects of vildagliptin in insulin-treated type 2 diabetes (T2DM) patients without overt chronic kidney disease." (PMID 32267348, 2020). "Moreover, studies have shown that acute HIIT reduces blood glucose in patients with type 2 diabetes, and 10 weeks of HIIT improves systemic insulin sensitivity of obesity mice." (PMID 32922365, 2020). "Insulin pumps are primarily used for type-I diabetes, as the patient is reliant upon continuous insulin administration; continuous insulin infusion is not required by people with type-II diabetes." (PMID 32785196, 2020). "We can measure blood glucose to diagnose diabetes, which provides a marker of disturbed glucose homeostasis resulting from an absence of insulin in type-1 diabetes or insulin resistance in type-2 diabetes." (PMID 32373557, 2020). "In the Copenhagen City Heart Study, which comprised 68 patients with type 1 diabetes and 323 patients with type 2 diabetes, pulmonary injury assessed through FEV1 and FVC was somewhat more pronounced in those treated with insulin in comparison with those treated with diet or oral agents." (PMID 32344939, 2020). "More recently, pioglitazone treatment in insulin-resistant patients with recent ischaemic stroke or transient ischaemic attack (but without type 2 diabetes) resulted in a significant reduction in the occurrence of cardiovascular events." (PMID 31713012, 2020). "Dietary changes are often essential for controlling type-2 diabetes, regardless of the insulin requirement." (PMID 32843013, 2020). "Annual excess costs for type 2 diabetes were estimated to be €499.49 for patients with type 2 diabetes and no antihyperglycemic treatment and range up to €5724.91 for insulin treated patients with type 2 diabetes." (PMID 33198734, 2020). "Type 2 diabetes occurs when the different parts of the body become immune to insulin and pancreas is not able to produce the required amount of insulin." (PMID 32790643, 2020). "Similar findings have been described, where total adiponectin had a significant inverse relation with HOMA-IR and obesity, and its low concentration was an essential determinant of insulin sensitivity and HDL in children and may predict type 2 diabetes." (PMID 31552725, 2020).
type 2 diabetes (continued). "Two recent meta-analyses involving 1077 participants with type 2 diabetes showed no effectiveness regarding changes in HbA1c, fasting glucose or fasting insulin levels after 12 or 24 weeks of CPAP treatment." (PMID 32260419, 2020). "In Type 2 Diabetes (T2D), the body becomes resistant to insulin or the pancreas does not produce adequate insulin." (PMID 32128205, 2020). "Prediabetics secrete more insulin to maintain normal blood sugar levels, but over time the pancreas cannot maintain this extra insulin release, and type 2 diabetes develops in the absence of control measures." (PMID 32604970, 2020). "Intermediate cells, although with an unaffected morphology, have been observed in non-diabetic controls and before in type 2 diabetes human islets, albeit with insulin granules." (PMID 32424134, 2020). "The most prevalent form of this condition is type 2 diabetes, where pancreatic beta cell failure usually, though not always, occurs in the face of insulin resistance in other tissues." (PMID 32350566, 2020). "Although the gene expression in the liver for type II diabetes mellitus signaling was activated, in the current experiment mice remained insulin-resistant without progression toward type II diabetes." (PMID 32883049, 2020). "In a recent previous study, we have showed, in type 2 diabetes without pregnancy, that insulin treatment can modulate immunological parameters, through immune cell subpopulation and cytokines, and confer to these patients a protective Th2 phenotype." (PMID 32626786, 2020). "An impairment on insulin secretory function of β-cells as well as the increasing of β-cell apoptosis are the principal abnormalities which lead to insulin resistance in liver, muscle and adipose tissue; and eventually to the development of type 2 diabetes mellitus (T2DM)." (PMID 33042011, 2020). "This lack of sensitivity to insulin action stimulates the appearance of type-2 diabetes mellitus due to the permanent high level of glucose in blood." (PMID 32927739, 2020). "This hypothesis is supported by findings of altered expression of genes encoding metabolic pathways in Type II diabetic patients such as, insulin-induced activity of IR, IRS, PI3K, AKT and GLUT4 have been reported to be reduced in Type II diabetes." (PMID 32670384, 2020). "As patients on insulin users often have a longer duration of type 2 diabetes, more complications and thus a more severe type 2 diabetes, disease severity is unlikely to represent a major confounder in our study." (PMID 32616483, 2020). "Fasting C-peptide was a strong predictor of newly subjects diagnosed with type 2 diabetes independent of BMI, waist circumference, and insulin (OR: 10.85; 95% CI: 2.27–51.8)." (PMID 32957570, 2020). "The aim of our study was to evaluate the association between baseline plasma C-peptide level and the development of type 2 diabetes independent of glucose and insulin levels and to examine potential effect-modification by variables related to kidney function." (PMID 32957570, 2020). "Taken together, metformin treatment had no glucose-lowering and insulin sensitivity-improving effect in db/db mice with type 2 diabetes; thus, the effects observed in this study were independent of glucose and insulin plasma concentrations." (PMID 32884086, 2020). "The db mouse model of type II diabetes is not primarily dependent on blood glucose control hormone and insulin secretion but is affected by β-cell dysfunction and insulin resistance." (PMID 32698784, 2020). "SNARE regulators may provide a novel target for type 2 diabetes therapies given their regulation of the secretion of key metabolic hormones, including not only GLP-1, but also insulin." (PMID 31918914, 2020). "Despite other reports linking phosphorus metabolites with insulin sensitivity, we found that type 2 diabetes status did not influence the in vivo metabolic phenotype (data not shown), and therefore, all subjects were grouped for correlative analyses." (PMID 32468656, 2020).
type 2 diabetes (continued). "Type 2 diabetes is distinguished by hyperglycemia, insulin resistance, relative lack of insulin, and with micro‐ and macrovascular disease." (PMID 31161658, 2020). "This study suggested that inhibition of fatty acid oxidation would not improve insulin sensitivity in patients with type 2 diabetes." (PMID 32595948, 2020). "Since metformin treatment of type 2 diabetes—but not metformin combined with insulin treatment—increased recent thymic emigrants and naïve T-cell populations, perhaps that benefit is greater with metformin than other type 2 diabetes treatments?" (PMID 32765940, 2020). "The other possibility is that with impaired insulin signalling overnight fasting is not sufficient to reach a steady state, therefore fasting hyperglycaemia in T2D is a non-steady state phenomenon in type 2 diabetes." (PMID 33365205, 2020). "In type 2 diabetic patients, glycogenolysis does not contribute to the hepatic glucose production and insulin loses its ability to reduce gluconeogenesis." (PMID 33679386, 2020). "In particular, ER stress may contribute to the development of Type 2 Diabetes (T2D) and Cystic Fibrosis Related Diabetes (CFRD), where evidence of impaired Insulin processing, including elevated secreted Proinsulin/Insulin ratios, are observed." (PMID 32433667, 2020). "International guidelines recommend the initiation of insulin when people with type 2 diabetes have signs and symptoms of acute decompensation that are no longer controlled by oral hypoglycemic drugs and lifestyle." (PMID 32406854, 2020). "Type 2 diabetes patients treated with insulin, metformin and a-glucosidase inhibitors showed lower circulating sRAGE levels than Type 2 diabetes patients not treated with these agents." (PMID 33187505, 2020). "GLP-1 is an incretin, which stimulates insulin secretion from pancreatic β-cell in a glucose-dependent fashion, and increasing and stabilizing GLP-1 levels is an important strategy to manage type 2 diabetes." (PMID 32932138, 2020). "In fact, the feedback loop is useful to depict the situation in diabetes as long as the disease is seen as a problem due to lack of insulin (type 1 diabetes, T1D) or to insulin resistance (type 2 diabetes, T2D)." (PMID 32132928, 2020). "Type 2 diabetes (T2D) is a long-term metabolic disorder disease characterized by high blood sugar and relative lack of insulin." (PMID 31790971, 2020). "A common distinction is between Type 1 Diabetes, where the body fails to produce insulin, and Type 2 Diabetes (T2D), where it is the way in which the body uses insulin which is important." (PMID 33014961, 2020). "In contrast to the well-known high mitochondrial capacity of endurance-trained athletes, several (but not all) studies have found that insulin-resistant individuals with type 2 diabetes are characterised by impaired mitochondrial oxidative capacity." (PMID 32185462, 2020). "Dark chocolate and cocoa beverages containing 960 mg total polyphenols and 480 mg flavanols did not affect glucose and increased insulin levels in obese type 2 diabetes subjects given a high-fat breakfast." (PMID 33266002, 2020). "In type 2 diabetes there are non-zero insulin levels and therefore, a steady state is possible, but insulin itself plays little role in deciding the steady state glucose level." (PMID 33365205, 2020). "Reduction in PGC1α gene expression with reduction in insulin secretion and development of type 2 diabetes was already noticed." (PMID 33324349, 2020). "From these reports, it is however difficult to determine if traditional diagnostic methods can distinguish between Type 1 diabetes, which is insulin-dependent, and Type 2 diabetes (not insulin-dependent) and if treatment methods are distinctive for these two." (PMID 32526850, 2020). "G protein-biased ligands for GLP-1R have been shown to enhance insulin secretion in mouse models of type 2 diabetes without producing nausea, a common adverse effect of GLP-1R agonists, thus allowing higher doses to be used." (PMID 31330984, 2019).